TGFBR1 (transforming growth factor beta receptor 1)
Diseases named in the same sentence as TGFBR1 in open-access papers (continued):
Sharing a sentence is not in itself a finding about the gene and the disease.
breast carcinoma (continued). "Other studies that included participants of similarly mixed ethnicities but from other states in the United States did not confirm an association between TGFBR1*6A and breast cancer risk." (PMID 35853889, 2022). "Overall, the unbiased gene expression analysis revealed that TGFBR1*6A alters the expression of known pro- and anti-metastatic effectors, which may contribute to its effect on breast cancer progression." (PMID 35853889, 2022). "However, the stably transfected TGFBR1*6A MCF-7 breast cancer cells exhibited enhanced cell growth, migration, and invasion." (PMID 35853889, 2022). "First, it is imperative to firmly establish whether TGFBR1*6A signaling is a signal peptide or receptor-mediated in various breast cancer subtypes and cell lines." (PMID 35853889, 2022). "For women of Asian and Middle Eastern descent, TGFBR1*6A association with breast cancer risk was neither significant nor protective." (PMID 35853889, 2022). "Although there are differences between our results and those obtained with breast cancer cells, site specificity and tumor specificity for the role of TGFBR1*6A may be the reason for the difference since TGF-beta signaling differs within tissues of the body." (PMID 20429896, 2010). "There was no overall association with TGFBR1 6A allele and breast cancer, neither in the familial risk cohort (P=0.17) nor in the population-based cohort (P=0.25) compared to controls." (PMID 17848956, 2007). "In conclusion, there was no overall association of the TGFBR1 variants *6A and Int7G24A and breast cancer in two breast cancer cohorts from the Stockholm region." (PMID 17848956, 2007). "In four main subtypes of breast cancer, elevated expression of BMPR1B and ACVR2B were seen in Luminal A subtype, while BMP4, GDF15 and ACVR1B were higher in Luminal B, TGFBR1 and BMP8A were higher in HER2 positive, BMP2, BMP6 and GDF5 were higher in TNBC." (PMID 37333824, 2023). "The relationship between the expression levels of TGFBR1 and TGFBR2 and immune cell infiltration in different breast cancer subtypes was also analyzed." (PMID 34485309, 2021). "Through analysis of the TIMER database, we found that the expression of TGFB1, TGFBR1, and TGFBR2 are correlated with the infiltration levels of various immune cells in breast cancer." (PMID 34485309, 2021). "TGF-β (TGFBR1 is TGF-β receptor 1) can induce the upregulation of Wnt3 and the β-catenin pathway in breast cancer cells." (PMID 34225723, 2021). "More specifically, TGFBR1 and FGFR1 in combination with highly expressed E2F1 induce the most invasive phenotype in bladder cancer, whereas in breast cancer, it is the combined action of TGFBR2, EGFR, and E2F1 that triggers high levels of invasiveness." (PMID 28775339, 2017). "Studies in breast cancer cells showed that NRP1 and NRP2 have a similar affinity for TGFBR1, whereas NRP2 has a higher affinity for TGFBR2 that TGFBR1." (PMID 26923176, 2016). "Several other studies from the US consisting of >80% Caucasians and <20% non-Caucasians reported similar TGFBR1*6A allelic frequency of 5.6–10.0% among breast cancer patients." (PMID 35853889, 2022). "These include the signaling gene TGFBR1, the proto-oncogene MYB as well as many immune-related genes such as CCR7 and FCRL3, reinforcing evidence for a role of immune components in influencing breast cancer patients’ prognosis." (PMID 28059167, 2017). "TGFBR1*6A has been shown to enhance the migration and invasion of MCF-7 breast cancer cells." (PMID 20429896, 2010). "In addition, the cell surface receptor category includes transforming growth factor-beta receptor genes (TGFBR1 and TGFBR3), and that the elevated TGFBR levels could induce collagen expression in metastatic breast cancer cells." (PMID 32315343, 2020).
pancreatic cancer (38 papers, 2002 to 2026). "BBR binds to the intracellular domain of transforming growth factor beta receptor 1 (TGFBR1) in pancreatic cancer, protecting endothelial barrier function from disruption induced by TGF-β1-overexpressing tumor cells and mitigating lung metastasis." (PMID 41585886, 2025). "Based on these findings, we propose TGFBR1 trafficking as a potential target for reprogramming CAFs, controlling desmoplasia, and tackling these aggressive features in pancreatic cancer." (PMID 41062852, 2025). "Overall, these data indicate that BBR reduces metastasis of pancreatic cancer cells by interacting with the intracellular kinase domain of TGFBR1 to prevent TGF-β1-induced damage to endothelial barrier." (PMID 36500723, 2022). "The LINC00462 promotes pancreatic cancer invasiveness through the miR-665/TGFBR1-TGFBR2/SMAD2/3 pathway." (PMID 36104680, 2022). "Targeting the TGFB axis has advanced rapidly in solid malignancies with phase II trials of a small molecule inhibitor of TGFBR1, demonstrating improved overall survival in hepatocellular carcinoma and unresectable pancreatic cancer." (PMID 35406544, 2022). "Briefly, we found that mmu-miR-688 and mmu-miR-30c-1* targeting Tcf712 and Cdk4 are involved in colorectal and pancreatic cancer, respectively, while the same miRNAs targeting Bad, Mapk10, Mapk3 and Tgfbr1 are involved both in pancreatic as well as colorectal cancer." (PMID 22245972, 2012). "In addition, linc00462 promotes the invasiveness of pancreatic cancer cells via regulating the miR-665/TGFBR1-TGFBR2/SMAD2/3 pathway, hence it could promote cell progression." (PMID 35310430, 2022). "Similarly, TIPE2 overexpression could decrease the protein level of TGFβ1 and phosphorylation of TGFBR1 in pancreatic cancer." (PMID 34249724, 2021). "Furthermore, TIPE2 could not only inhibit the secretion of TGFβ1, but also decrease the phosphorylation of TGFBR1 in pancreatic cancer cells." (PMID 34249724, 2021). "Intracellular miR-665 transfection led to the decreased expression of TGFBR1 and TGFBR2, suppressing the proliferation and invasion of human pancreatic cancer cells." (PMID 39838364, 2025). "The overexpression of LINC00462 improved TGFBR1 and TGFBR2 expression levels to activate the SMAD2/3 signaling pathway in pancreatic cancer." (PMID 33622186, 2021). "LINC00462 participates in the miR-666/TGFBR1-TGFBR2/SMAD2/3 or AKT signaling pathways to promote tumor invasion and progression in pancreatic cancer and hepatic cancer." (PMID 34238114, 2021). "In 2022, we studied the impact of berberine on lung metastasis in pancreatic cancer and found that berberine can function as a transforming growth factor-beta receptor 1 (TGFBR1) inhibitor, preventing pancreatic cancer cells from breaking through endothelial cells and metastasizing." (PMID 39944624, 2025). "Pancreatic cancer cells (PANC-1, SW1990, and AsPC-1) expressed higher levels of TGF-β1 compared to normal pancreatic ductal epithelial cells, and inhibition of TGFBR1 in endothelial cells blocked the inhibitory effect of BBR on trans-endothelial migration of AsPC-1 cells." (PMID 36500723, 2022). "In addition, TGFBR1 can increase the infiltration levels of the regulatory T cells (Tregs) and CAFs in both triple-negative breast cancer (TNBC) and pancreatic cancer tissues, and more importantly, suppress the intratumoral infiltration levels of T lymphocytes and activated dendritic cells (DCs)." (PMID 37328484, 2023). "Interestingly, the signalling pathway of transforming growth factor β (TGFβ) is often inactivated in the tumour cells and the genes for the TGFβ type I receptor (TGFβ-RI/ALK5), TGFBR1 and the type II receptor (TGFβ-RII), TGFBR2, are selective targets of genetic inactivation in pancreatic cancers." (PMID 30366420, 2018).
Loeys-Dietz syndrome (37 papers, 2007 to 2026). "Vascular Ehlers-Danlos syndrome, resulting from mutations in the COL3A1 gene, and Loeys-Dietz syndrome, linked to TGFBR1 and TGFBR2 mutations, are known to predispose individuals to arterial dissections due to connective tissue fragility." (PMID 41362507, 2025). "Among the genes queried, COL3A1 and aggregated testing of Loeys-Dietz syndrome-associated genes (TGFBR1, TGFBR2, SMAD2, SMAD3, TGFB2, TGFB3) were the leading signals of enrichment, consistent with prior studies [21•, 24, 25]." (PMID 37979122, 2023). "Actually, this patient was found to harbor a variant in the TGFBR1 gene linked to Loeys-Dietz 1 syndrome and the presence of a bicuspid valve." (PMID 37761403, 2023). "Rare germline TGFBR1/2 mutations lead to Loeys-Dietz syndrome (LDS) which is a sinister genetic connective tissue disorder characterized by early-onset aortic aneurysm, craniofacial features, and allergic diseases." (PMID 37029342, 2023). "Loeys-Dietz syndrome, caused by mutations in TGFBR1 and TGFBR2, is characterized by vascular and skeletal abnormalities and arterial tortuosity, aneurysms and aortic dissection are the common presentations." (PMID 35414028, 2022). "TGFBR1 mutations associated with Loeys Dietz syndrome were found to be inactivating for canonical TGFβ signaling in co-transfection studies with a luciferase reporter or EGFP-tagged SMAD2 in HEK293 cells." (PMID 33256177, 2020). "The great majority of TGFBR1 mutations in patients with Loeys Dietz syndrome are missense variants clustered in or near the region of the gene that encodes the cytoplasmic serine/threonine kinase domain." (PMID 33256177, 2020). "Loeys Dietz syndrome can be caused by mutations in TGFBR1 and several other genes encoding for components of the TGFβ signaling pathway including TGFBR2, SMAD3, TGFB2 and TGFB3." (PMID 33256177, 2020). "A 50-year-old woman with MSSE was found to carry a missense mutation in the serine kinase domain of TGFBR1, previously reported only in Loeys Dietz syndrome (c.1459C > T, p.Arg487Trp)." (PMID 33256177, 2020). "It is likely that the TGFBR1 variants that predispose to Loeys Dietz syndrome are less common than other classes of pathogenic variants in the gene." (PMID 33256177, 2020). "The mechanism by which missense kinase domain TGFBR1 mutations cause Loeys Dietz syndrome is complex and incompletely understood." (PMID 33256177, 2020). "The reproductive fitness of carriers of TGFBR1 variants that cause Loeys Dietz syndrome is likely to be reduced because of the substantial risk of early death from aortic dissection and other vascular complications of the condition." (PMID 33256177, 2020). "The spectrum of TGFBR1 mutations in patients with Loeys Dietz syndrome and patients with MSSE is different." (PMID 33256177, 2020). "For instance, mutations in either TGF-β receptor type I (TGFBR1) or type II (TGFBR2) are associated with Loeys-Dietz syndrome." (PMID 31241461, 2019). "A surgical series of Loeys-Dietz syndrome confirmed high rates of proximal aortic surgery, where 18% with TGFBR1, 48% with TGFBR2, and 27% with SMAD3 pathogenic variants underwent surgery." (PMID 31795342, 2019). "The initial description of Loeys-Dietz syndrome reported pathogenic variants in the genes encoding for the transforming growth factor beta receptor 1 (TFGBR1) and 2 (TGFBR2)." (PMID 31795342, 2019). "Our high prevalence of mitral valve prolapse in Loeys-Dietz syndrome confirmed findings in a previous series of TGFBR1- and TGFBR2 pathogenic variants." (PMID 31795342, 2019). "Mutations in SMAD3, have been identified in up to 2% of patients with familial thoracic aneurysms leading to acute aortic dissection Patients with the Loeys-Dietz syndrome have mutations in receptors for TGF-β (TGFBR1 and TGFBR2)." (PMID 26925344, 2016).
Loeys-Dietz syndrome (continued). "For example, gene mutation causing systemic diseases such as Marfan syndrome (FBN1), Ehlers-Danlos syndrome (COL3A1), and Loeys-Dietz syndrome (TGFBR1/2) could significantly increase the risk of aortic dissection." (PMID 37596272, 2023). "If uncommon inherited variants at a second locus are required for development of tumors in TGFBR1 mutation carriers then only a small proportion of patients with TGFBR1 mutations ascertained because they have Loeys Dietz syndrome would be expected to have MSSE." (PMID 33256177, 2020). "Therefore, we performed this observational case-matched comparison of a Loeys-Dietz syndrome group including 83 individuals with a pathogenic variant in the three most common genes identified in Loeys-Dietz syndrome (TGFBR1, TGFBR2, and SMAD3) gene." (PMID 31795342, 2019). "Finally, mutations in TGFBR1 gene, known to affect vascular integrity in Marfan and Loeys-Dietz syndromes, have to be taken into consideration for the design of probes to measure TGFBR1 expression and for the design of specific therapeutic inhibitors." (PMID 22136666, 2011). "Finally, in our series, 17% of TGFBR1 pathogenic variants required extension of proximal aortic surgery into the aortic arch, where others reported aortic arch replacement in 11%, 18% and 45% of Loeys-Dietz syndrome patients." (PMID 31795342, 2019). "Among them, 51 patients had genetically confirmed HTAD (Marfan syndrome (FBN1), Loeys-Dietz syndrome (TGFBR1, TGFBR2, SMAD3, TGFB2), vascular Ehlers-Danlos syndrome (COLSA1), and non-syndromic HTAD (ACTA2, MYH11, MYLK))." (PMID 41310758, 2025). "TGFBR1/2 and SMAD2/3 encode proteins involved in TGF-β signaling and mutations in these genes cause Loeys-Dietz syndrome (LDS) in patients (TGFBR1; LDS1; MIM 609192, TGFBR2; LDS2; MIM 61068, SMAD2; LDS6; MIM 619656, SMAD3; LDS3 (AOS); MIM 613795)." (PMID 35492343, 2022). "The spectrum of TGFBR1 mutations in MSSE and the allelic disorder Loeys Dietz syndrome (characterized by developmental anomalies and thoracic aortic aneurysms) differ." (PMID 33256177, 2020). "Within the Loeys-Dietz syndrome group, mean freedom from death was similar with TGFBR1 (70 ± 3 years, 95% CI 64–77), TGFBR2 (73 ± 5 years, 95% CI 63–83), and SMAD3 pathogenic variants (76 ± 6 years, 95% CI 64–89; p = 1.000)." (PMID 31795342, 2019). "TGFBR1 (TGF beta receptor 1), a tan module gene, when mutated in humans causes the Loeys-Dietz syndrome that is associated with cerebral aneurysms and arterial dissections." (PMID 30836997, 2019). "Within the Loeys-Dietz syndrome group, mean freedom from proximal aortic surgery was similar with TGFBR1 (48 ± 5 years, 95% CI 38–58), TGFBR2 (49 ± 5 years, 95% CI 39–58), and SMAD3 pathogenic variants (68 ± 6 years, 95% CI 55–80; p = 0.143)." (PMID 31795342, 2019). "These include syndromic diseases associated with aortic aneurysms, including Marfan’s and Loeys Dietz Syndromes (LDS), due to mutations in TGFβ signaling genes FBN1, TGFBR1, TGFBR2, TGFB2, and TGFB3." (PMID 30307970, 2018). "Loeys-Dietz syndrome (LDS) is an autosomal dominant connective tissue disorder characterized by aggressive aortic pathology, primarily caused by pathogenic variants in genes such as TGFBR1." (PMID 42164325, 2026). "Among these, Loeys-Dietz syndrome (MIM # 609,192) shows mutations in other genes which are involved in the same pathway of FBN1 and include TGFBR1 (MIM * 190,181), TGFBR2 (MIM * 190,182), SMAD3 (MIM * 603,109), TGFB2 (MIM * 190,220), TGFB3 (MIM * 190,230) and SMAD2 (MIM * 601,366)." (PMID 39008115, 2024).
Loeys-Dietz syndrome (continued). "Heterozygous mutations in the genes encoding TGF-β receptors 1 and 2 (TGFBR1 and TGFBR2, respectively) cause Loeys-Dietz syndrome, an autosomal dominant aortic aneurysm syndrome, which predisposes patients to aggressive vascular disease with widespread systemic involvement." (PMID 35234888, 2022). "In addition, mutations in the TGF-β receptor genes (TGFBR1 and TGFBR2) result in Marfan-like syndromes with aortic aneurysms and dissections as well, named ‘Loeys-Dietz Syndrome’." (PMID 25238161, 2014). "Moreover, mutations in several genes of the TGFβ signaling pathway, e.g., ALK1, ALK5, ENG, SMAD4, and TGFBR1/2, are known to cause Marfan or Loeys-Dietz syndrome, both frequently associated with vascular pathologies such as intracerebral hemorrhages or hemorrhagic hereditary telangiectasia." (PMID 34572573, 2021). "Similarly, while TGFBR1- and TGFBR2-related Loeys-Dietz syndrome are included in the IUIS gene list for IEI, SMAD3-related Loeys-Dietz syndrome is not, despite manifesting with many of the same symptoms." (PMID 37215141, 2023).
liver fibrosis (33 papers, 2013 to 2026). "To characterize the effects of TGFBR1 and TGFBR2 on liver fibrosis, we knocked down the expression of TGFBR1 and TGFBR2 in HSC-T6 cells using siRNA transfection." (PMID 28518142, 2017). "However, a large number of inhibitors of TGFBR1 kinase have been designed and preclinically tested in various fibrosis-related diseases, and these may eventually be used to treat liver fibrosis." (PMID 28518142, 2017). "However, a key finding emerging from this study is that the antifibrotic efficacy of PDGFR and TGFBR1 tyrosine kinase inhibitors was dependent upon the factor driving the fibrosis, and this could explain why it has been so difficult to develop liver fibrosis therapies." (PMID 39656528, 2024). "TGFBR1 and TGFBR2 levels were increased by high levels of HOTTIP, which led to the progression of liver fibrosis." (PMID 34899344, 2021). "In liver fibrosis, TGF-β1 downregulates miR-9 expression by promotor methylation, whereas TGFBR1 (ALK5) and TGFBR2 have been established as direct targets of miR-9." (PMID 30081513, 2018). "The circRNA cVIM may act as a sponge for miR-122-5p and miR-9-5p to enhance expression of TGFBR1 and TGFBR2 and promote activation of the TGF-β/Smad pathway, thereby accelerating the progression of liver fibrosis." (PMID 38243118, 2024). "These evidences suggested that miR-130a-3p could inhibit TGF-β/Smads signaling, at least in part, via TGFBR1 and TGFBR2 to affect the activation of HSCs and the phenotype of macrophages involving the development of liver fibrosis." (PMID 34421906, 2021). "Among the 28 target genes, we considered that MAPK1, TGFBR1, and TGFBR2 represent the potential target genes that could be regulated by miR-130a-3p and involved in the liver fibrosis of schistosomiasis." (PMID 34421906, 2021). "Notably, high levels of HOTTIP downregulate miR-148a, increase the expression levels of the miR-148a targets TGF-beta receptor type-1 (TGFBR1) and TGF-beta receptor type-2 (TGFBR2) and thus contribute to liver fibrosis." (PMID 32098245, 2020). "Further studies revealed that cVIM, mainly expressed in the cytoplasm, may act as a sponge for miR-122-5p and miR-9-5p to enhance expression of type I TGF-β receptor (TGFBR1) and TGFBR2 and promotes activation of the TGF-β/Smad pathway, thereby accelerating the progression of liver fibrosis." (PMID 38243118, 2024). "Our results collectively suggest that cVIM acts as a sponge for miR-122-5p and miR-9-5p to enhance expression of TGFBR1 and TGFBR2, leading to the phosphorylation of Smad2 (a downstream mediator of TGF-β signaling), which finally promotes TGF-β/Smad pathway and the progression of liver fibrosis." (PMID 38243118, 2024). "Other known liver fibrosis-related genes, ASMA, TGFB1, and TGFBR1, were not suppressed at the non-toxic concentration, suggesting that apigenin’s effect is directed to a specific subset of fibrogenesis-related pathways." (PMID 28256512, 2017).